ATR (ATR checkpoint kinase)
Diseases named in the same sentence as ATR in open-access papers (continued):
Sharing a sentence is not in itself a finding about the gene and the disease.
cancer (continued). "Other than predicative biomarkers, data coming from ATR inhibitor-based combinational trials could shed light on whether we can expand this therapy to HR-proficient cancers and whether this approach can serve as a rescue therapy for patients who have progressed through PARP inhibitors." (PMID 31018854, 2019). "Finally, we investigated whether ATR was also involved in regulating the activity of CLA derivatives in cancer cells." (PMID 31575977, 2019). "ATR inhibitors are currently in clinical trials for a broad spectrum of tumor types, and it will be of considerable interest to assess whether Fanconi-BRCA mutations provide a biomarker of response to ATR inhibition across human cancer subtypes." (PMID 31721781, 2019). "However, if inhibition of GSK3-β activates Chk1, a GSK3-β inhibitor might be inhibiting cancer growth at the same time as promoting the pro-survival pathway ATR-Chk1." (PMID 31362447, 2019). "Data from ATR inhibitor-based combinational trials might lead to future expansion of this therapy to homologous recombination repair pathway-proficient cancers and potentially serve as a rescue therapy for patients who have progressed through poly ADP-ribose polymerase inhibitors." (PMID 31018854, 2019). "In addition, inhibition of DDR kinases, such as ATM and ATR, has been revealed to increase the response to ionizing radiation in some kinds of cancer including ovarian and cervical carcinoma in vitro, while was not capable of increasing the response to platinum drugs." (PMID 30975222, 2019). "Furthermore, a role for ATR-dependent RSR in driving these changes might explain the requirement for ATR cancer cell survival as reflected by the efficacy of ATR inhibitors in killing tumour cells." (PMID 29950452, 2018). "The evidence that BRD4 positively regulates DNA damage checkpoint activation and DSB repair, implicates that its pharmacological inhibition by BETi may increase sensitivity of cancer cells to DDR or ATR inhibitors defining a possible combination strategy in specific tumor settings." (PMID 30466442, 2018). "Therefore, simultaneous inhibition of DNA2 and ATR could have an additive or synergistic effect in killing cancer cells." (PMID 29773570, 2018). "Other proteins involved in DDR such as ATM, ATR, CHEK1, CHEK2, DSS1, RAD51, NBS1 and those whose deficiency causes Fanconi anaemia have been assessed in preclinical studies to determine PARP inhibitor sensitivity, with early positive results in a variety of cancer cell lines." (PMID 29069866, 2017). "Cdc7-Dbf4 kinase also is an excellent target for therapeutic strategies that not only block DNA synthesis at the beginning but also sensitize cancer cells to DNA damage by targeting HSP90/ATR/ATM, which may a promising approach to enhance the therapeutic effect of radiation or chemotherapy." (PMID 29209046, 2017). "On the other hand, knockdown of ATR, CHK1 or WEE1 by siRNA or inhibition of them by using specific inhibitors causes re-firing of DNA replication and thus further enhance replicative stress and lead to more DNA damage, which eventually causes cancer cell death." (PMID 28262781, 2017). "Besides the ability to inhibit NF-κB/STAT3, we show that GL may target cancer cell progression by the activation of ATM/ATR pathway, inducing a rapid CDC25C degradation in DU145 cells." (PMID 26683224, 2016). "Importantly, ALT was recently suggested to render cancer cells hypersensitive to ATR inhibitors." (PMID 26891131, 2016). "Importantly, cancer cells with elevated replication stress activate ATR/Chk1 and may depend more on these kinases for cell survival compared to normal cells." (PMID 25774168, 2015).
cancer (continued). "The DNA damage response kinase ATR may be a useful cancer therapeutic target." (PMID 25965342, 2015). "However, several recent studies demonstrate that cancer cells may be considerably more sensitive to the partial ATR inhibition compared to healthy cells." (PMID 26295265, 2015). "Hence, it is possible that cancer cells with inherent reduced expression of ATR, Chk1, or Wee1 may respond to low concentrations of checkpoint kinase inhibitors, whereby normal cells could be spared." (PMID 25774168, 2015). "Moreover, deeper insight into processes triggered in cancer cells sensitive to ATR inhibition may in the future lead to identification of potential markers of sensitivity to VE-821 treatment." (PMID 25003641, 2014). "Therefore, upregulated ATR activity in COX-2 overexpressing cancer cells may compensate for the ATM activity inhibited by gefitinib, and thereby prevent MC." (PMID 20731837, 2010). "However, analysis of 126 index cases suggests that ATR mutations do not play a major role in hereditary susceptibility to these cancers." (PMID 15987455, 2005). "However, various cell lines in which ATR has been inactivated exhibit genetic instability, and this may predict proneness to cancer." (PMID 15987455, 2005). "For tumors with low SLFN11 expression, systematically evaluate the efficacy of the combination regimens of ATR inhibitors, ATM inhibitors, CHK1 inhibitors, and WEE1 inhibitors with standard chemotherapy in different cancers." (PMID 40766331, 2025). "Future priorities include validating novel biomarkers (SBS39, miR-622) and combination therapies (PARPi with ATR inhibitors) to overcome resistance and broaden HRD’s applicability across cancers." (PMID 40864792, 2025). "HRD cancer cells also heavily rely on CHK1, a key downstream effector of ATR that stabilizes stressed replication forks and enforces the S and G2/M checkpoints by inactivating CDC25 phosphatases." (PMID 41190241, 2025). "The inhibition of ATR has been shown to induce an HRD status, underscoring its potential as a therapeutic target in cancer treatments." (PMID 39968096, 2025). "Together, our data demonstrate that ATR upregulates LSS, which promotes mTORC1 activity through cholesterol in cancer cells." (PMID 40514450, 2025). "In this study, we demonstrated that FAM111B expression correlates with 17 HR repair proteins, including ATM, ATR, and BRCA1/2, in 30 out of 33 of the studied cancers." (PMID 40243892, 2025). "First, replication stress–inducing agents, such as inhibitors of ATR, WEE1, and CHK1/2, are being explored in clinical trials with promising early results specifically in HR-proficient cancers." (PMID 40392598, 2025). "DNA-PK, ATR, and ATM inhibitors have displayed significant potential effects in preclinical studies as targeted therapies for cancer." (PMID 40256842, 2025). "Recent studies have shown that targeting synthetic lethal partners of ARID1A uncovers selective vulnerabilities in ARID1A-mutant cancers, including inhibition of EZH2, ATR, PARP, and HDAC6." (PMID 40750787, 2025). "In PDAC cancer cell lines, we evaluated the abundances of TOPBP1, p-ATR, p-ATM, p-CHK1, and p-CHK2 proteins—key genes in the ATR and ATM pathways." (PMID 39920847, 2025). "Medicinal chemists have made significant strides in leveraging key biological discoveries about the roles of DNA-PK, ATR, and ATM in the initiation and progression of cancer to design tractable chemical architectures exerting their modulation." (PMID 40256842, 2025). "High levels of replication stress make cancer cells vulnerable to therapies targeting DNA damage response (DDR) proteins, such as ataxia telangiectasia and Rad3-related (ATR) protein kinase." (PMID 41417226, 2025).
cancer (continued). "At present, the commonly used method to treat cancer is to activate the cancer cell cycle checkpoints such as ATM, ATR, CHK and other genes, so that cancer cells can die normally." (PMID 39944835, 2025). "Studies indicate that the combination of ATR inhibitors and immune checkpoint inhibitors (such as PDL-1) shows synergistic anti-tumor activity in cancers like castration-resistant prostate cancer." (PMID 40240755, 2025). "A critical question for the clinical development of ATR inhibitors is their relationship with PARP inhibitors (PARPi), particularly in BRCA-mutant cancers, where PARPi are an established standard of care." (PMID 41409249, 2025). "Clinically, DNA damage repair (DDR) inhibitors, including ATR inhibitors, ATM inhibitors, and DNA-PK inhibitors, have been applied to treat cancers like advanced solid cancers." (PMID 41285712, 2025). "These and other published results exemplify the opportunity to discover novel cancer vulnerabilities by pharmacological combinations targeting ATM, ATR and Chk1/2, especially in DDR impaired genetic backgrounds." (PMID 40422251, 2025). "In G401 cells, the depletion of MYC results in a similar decreased level of both ATR and RAD51, suggesting that MYC generally controls DNA repair protein expression in SWI/SNF-altered cancer cell lines, as has been seen in other cancers." (PMID 40647552, 2025). "DNA sensors ATM and ATR are both involved in detecting these lesions, initiating DDR pathways responsible for subsequent DNA repair and promoting cancer cell survival." (PMID 40514666, 2025). "ATR and CHK1/2 inhibitors show potential as prospective treatments for TNBC by focusing on the DDR and interfering with cell cycle regulation in cancer cells." (PMID 38539474, 2024). "We also found that 5-FU-treated RER-positive HCT116 cancer cells (at pHe 7.4) exhibited a dose-dependent increase in phosphorylated ATM, ATR, CHK1, and CHK2, reaching levels observed in untreated acid-exposed cancer cells (pHe 6.5)." (PMID 38366255, 2024). "Our results confirmed the synergistic effect of ATR/Chk1 inhibitors and gemcitabine in OTUD6A-overexpressing BCa cells, suggesting the possible beneficial effects of targeting ATR/Chk1 in cancers with high expression of OTUD6A and CDC6." (PMID 38685067, 2024). "ATR and CHK1/2 inhibitors show potential as prospective treatment options for TNBC by interfering with the cell cycle regulation of cancer cells." (PMID 38539474, 2024). "Essential proteins frequently overexpressed in cancer cells include PARP, DNA-PKcs, BRCA1/2, ATM, ATR, and Chk1/2." (PMID 39372203, 2024). "A similar pattern of ATM, ATR, and checkpoint kinase activation was observed in 5-FU-treated RER-negative HT-29 cancer cells at pHe 7.4 vs. untreated HT-29 cells at pHe 6.5." (PMID 38366255, 2024). "Cancer cells often have rapid division rates and are more vulnerable to specific DDR inhibitors like ATR and DNA-PK inhibitors." (PMID 39372203, 2024). "We assessed the ability of an ATR inhibitor, AZD6738, to sensitize cancer cell lines of various histologic types to photon and proton radiotherapy." (PMID 39235982, 2024). "Ataxia telangiectasia and Rad3-related protein (ATR) is an essential kinase that activates cell cycle checkpoint signaling in response to DNA stress and damage and plays an important role in cancer cell survival." (PMID 39594898, 2024). "Their capacity to specifically attach to and possibly regulate the activity of proteins such as ATM, ATR, CHK1, and WEE1 reveals a pathway towards novel treatment approaches, emphasizing the essential role of DDR in the survival and growth of cancer cells." (PMID 38961104, 2024). "Following irradiation, a caspase-independent wave of CAD activation was observed in cancer cells, which depended on the phosphorylation of ICAD by ATM/ATR." (PMID 38977850, 2024).
cancer (continued). "Alterations in multiple different molecules and pathways in the DNA damage response are driving new drug development to target HR-proficient cancer cells, such as inhibitors of the CDK or P13K/AKT pathways, as well as ATR inhibitors." (PMID 38894867, 2024). "Until recently, the role of therapeutics targeting the DNA damage response such as PARP, ATR, DNA-PK and ATM for cancer treatment has largely focused on the tumor cells." (PMID 38402224, 2024). "Cancer cells chronically adapted to pHe 6.5 revealed a significant increase in phospho-ATM and phospho-ATR together with higher phospho-CHK1 and phospho-CHK2 levels (vs. cells maintained at pHe 7.4)." (PMID 38366255, 2024). "Clinical trials with AZD6738, an ATR inhibitor, and AZD1775 (NCT02617277), a WEE1 inhibitor, individually as well as in combination with durvalumab in patients with advanced cancers, are currently ongoing." (PMID 36900418, 2023). "In this review, we introduce the activation of the PI3K/AKT/mTOR signalling pathway in cancer and the mechanisms by which PIKK members ATM, ATR, and DNA-PK repair DNA damage." (PMID 37489050, 2023). "ATR inhibitors, including Berzosertib and Ceralasertib, can potentially act on ARID1A-mutant cancer." (PMID 38203635, 2023). "Both ATR and CDC7 inhibitors (ATRis and CDC7is) show excellent anti-tumor activity in a variety of preclinical cancer models and are currently being explored as potential anti-cancer agents in clinical trials." (PMID 37378325, 2023). "We here combined the results from a recently published genome‐scale cancer gene discovery screen and a comprehensive description of ATM and ATR targets to identify novel regulators of the DDR with a functional role in B‐cell lymphomagenesis." (PMID 37485814, 2023). "For a clinical implication, the synergism demonstrated in this study supports the rationale to further investigate the combination of PARP and ATR inhibitors in HRR-deficient cells beyond BRCA1/2 that may give advantages for cancer patients without germline mutations in BRCA1/2." (PMID 36794257, 2023). "Although numerically higher response rates were seen in cancers with low ATM protein, the benefit seen in these patients were possibly lower than that observed with other ATR inhibitors or in preclinical models given in a more continuous schedule." (PMID 37773077, 2023). "The potential usefulness of combined ATR and RNR inhibition has been evaluated in a number of studies on diverse adult cancers." (PMID 37097390, 2023). "Current evidence shows that APE2 can activate ATR/Chk1 DDR, which promotes faithful replication and acts antithetically to the development of cancer and thereby serves a role equivalent or similar to tumor suppressor." (PMID 36755963, 2023). "Using preclinical mechanistic approaches and clinical datasets, we establish functional ATM deficiency as a principal DNA repair defect in ES and the compensatory ATR signaling axis as a collateral dependency and therapeutic target in FET rearranged cancers." (PMID 37398210, 2023). "In summary, we discussed various aspects of R-loops in cancer, specifically focusing on their interplay with DNA repair proteins such as BRCA1, BRCA2, and ATR." (PMID 37108225, 2023). "Inhibitors of WEE1, ATR, CHK1 and PLK1 have also achieved preliminary response in certain types of cancer patients." (PMID 37679326, 2023). "In this review, we provide a current understanding of alterations and expression of APE2 in cancer, the function of APE2 in the immune response, and mechanisms of APE2 in ATR/Chk1 DNA damage response." (PMID 36755963, 2023).
cancer (continued). "The role of ATR and CHK1 inhibitors in the treatment of cancer will be revealed through results from current and planned clinical studies." (PMID 37511442, 2023). "As healthy cells do not have the same restricted DNA repair capacity typically found in cancer cells, we suggested that healthy cells—fibroblasts in our model system—should adapt better to inhibition of DDR, while targeting ATR or ATM with specific inhibitors." (PMID 36229655, 2023). "In cancer cells, the ATM-Chk2 pathway is often attenuated; thus, cancer cell survival often depends on the ATR-Chk1 pathway." (PMID 36765693, 2023). "DDR kinase inhibitors, such as those targeting PARP, ATM, ATR, DNA-PK, CHK1/2, BER, and WEE1, have been tested in clinical trials as a way to kill tumor cells, as cancer cells are more sensitive to compromised repair systems compared to normal cells." (PMID 36900418, 2023). "Finally, inhibiting APE2 may be combined with ATR inhibition for cancer therapy." (PMID 36755963, 2023). "Evidently, adavosertib can synergize with other cancer therapy agents that induce replication stress such as gemcitabine, CHK1, ATR, or PARP1 inhibitors, potentially by exacerbating replication stress to intolerable levels." (PMID 36632060, 2023). "Currently, several early-phase trials of agents targeting ATR in combination with a topoisomerase I inhibitor (NCT04514497, NCT02487095, and NCT03896503) are ongoing in cancers, including GEP-NECs." (PMID 37422534, 2023). "Combining ICB with RT, ATR, DNA-PKcs, and PARP inhibitors has been shown to improve outcomes in some cancer types, in large part due the activation of innate immune responses driven by the cGAS-STING pathway." (PMID 38201511, 2023). "The DDR pathways are promising targets for anti-cancer therapy, and various DDR-related genes are currently under clinical development, such as PARP, ATM, ATR, DNA-PK, CHK1, CHK2, and WEE1." (PMID 38041093, 2023). "For ATM-defective cancer cells (e.g. CLL cells), ATR becomes the main activator to regulate DNA replication stress, and inhibition of ATR can induce unrepaired DNA damage and result in the cells death." (PMID 37387166, 2023). "In conclusion, this work emphasizes the value of investigating the possible indications of the combination of PARP and ATR inhibitors for cancer treatments to enhance the efficacy of PARP inhibitors and expand their use to other groups of cancer patients." (PMID 36794257, 2023). "The PIKK family consists of ATR, ATM, DNA‐PKcs, mTOR, and hSMG, that are vital in cancer progression, autophagy, and survival following radiotherapy and chemotherapy." (PMID 36349142, 2022). "ATM inhibition, ATR inhibition, Chk1 inhibition, PARP inhibition, and WEE1 inhibition have all been shown to lead to cGAS-STING pathway activation and potentiation of cancer immunotherapy." (PMID 36362142, 2022). "At present, cell cycle checkpoint inhibitors (ATR, CHK1 and WEE1) have been already an general and effective measure for anti-cancer therapy." (PMID 35021154, 2022). "In our analysis, T‐ALL cell lines showed increased sensitivity to inhibitors of ATR (AZD6738, ceralasertib), CHK1/2 (AZD7762 and MK‐8776), and Wee1 (AZD1775, adavosertib) as measured by a reduced IC50 compared with other non‐T‐cell cancer cells." (PMID 35510955, 2022). "The ATR inhibitor AZD6738, with DNA-damaging agents, induces a canonical apoptotic response in several cancer types." (PMID 35413091, 2022). "Several other studies have provided evidence that DNA damage and stress signal is transmitted from protein kinase (ATM and ATR) and its downstream CHK1 and CHK2 target phosphorylation at different residues in cancer cells." (PMID 35946055, 2022).